TICAM2 (TIR domain containing adaptor molecule 2)
Description:
Functions as a sorting adapter in different signaling pathways to facilitate downstream signaling leading to type I interferon induction. In TLR4 signaling, physically bridges TLR4 and TICAM1 and functionally transmits signal to TICAM1 in early endosomes after endocytosis of TLR4. In TLR2 signaling, physically bridges TLR2 and MYD88 and is required for the TLR2-dependent movement of MYD88 to endosomes following ligand engagement. Involved in IL-18 signaling and is proposed to function as a sorting adapter for MYD88 in IL-18 signaling during adaptive immune response. Forms a complex with RAB11FIP2 that is recruited to the phagosomes to promote the activation of the actin-regulatory GTPases RAC1 and CDC42 and subsequent phagocytosis of Gram-negative bacteria. [Isoform 2]: Proposed to inhibit LPS-TLR4 signaling at the late endosome by interaction with isoform 1 thereby disrupting the association of isoform 1 with TICAM1. May be involved in TLR4 degradation in late endosomes.
Synonyms: TICAM-2; MyD88-4; TIRAP3; TIRP; TRAM
Tractability: Antibody: UniProt places it where antibodies can reach, with high confidence; its Gene Ontology location is reachable by antibodies, with high confidence.
Gene: Protein-coding gene on chromosome 5 (115,578,196 to 115,602,479, reverse strand). Ensembl gene ENSG00000243414.
Subcellular location: Cytoplasm (Isoform 1); Golgi apparatus; Cell membrane; Endoplasmic reticulum; Early endosome membrane; Late endosome membrane; Cell projection, phagocytic cup; Endoplasmic reticulum (Isoform 2)
Pathways (Reactome):
Immune System: Activation of IRF3, IRF7 mediated by TBK1, IKKε (IKBKE); IKK complex recruitment mediated by RIP1; IRAK2 mediated activation of TAK1 complex upon TLR7/8 or 9 stimulation; MyD88-independent TLR4 cascade; Neutrophil degranulation; Regulation of TBK1, IKKε (IKBKE)-mediated activation of IRF3, IRF7; TRAF6-mediated induction of TAK1 complex within TLR4 complex; TRIF-mediated programmed cell death; Toll Like Receptor 4 (TLR4) Cascade
Programmed Cell Death: Caspase activation via Death Receptors in the presence of ligand
Gene Ontology:
Molecular function: molecular adaptor activity; protein binding; signaling adaptor activity
Biological process: cellular response to lipopolysaccharide; phagocytosis; positive regulation of canonical NF-kappaB signal transduction; positive regulation of interleukin-18-mediated signaling pathway; positive regulation of toll-like receptor 4 signaling pathway; positive regulation of type I interferon production; toll-like receptor 4 signaling pathway; TRAM-dependent toll-like receptor 4 signaling pathway; innate immune response; lipopolysaccharide-mediated signaling pathway; TRIF-dependent toll-like receptor 4 signaling pathway; TRIF-dependent toll-like receptor signaling pathway; positive regulation of chemokine (C-C motif) ligand 5 production; response to other organism; signal transduction
Cellular component: cytoplasm; endosome; endosome membrane; phagocytic cup; plasma membrane; cytosol; secretory granule membrane; early endosome membrane; endoplasmic reticulum; Golgi apparatus; late endosome membrane
Genetic constraint (gnomAD): Loss-of-function variants: 10 observed, 10.72 expected, observed/expected ratio (o/e) 0.93, 90% interval 0.57 to 1.57. The upper end of that interval is the gene's LOEUF score, 1.57, which puts it in group 6 of 6, group 1 being the genes least tolerant of losing a copy. Missense variants: 304 observed, 288.77 expected, observed/expected ratio (o/e) 1.05, 90% interval 0.96 to 1.16. Synonymous variants: 113 observed, 103.53 expected, observed/expected ratio (o/e) 1.09, 90% interval 0.94 to 1.28.
Homologues: Orthologues: chimpanzee TICAM2 (99% identical), rat Ticam2 (76% identical), zebrafish ticam1 (28% identical).
Diseases named in the same sentence as TICAM2 in open-access papers:
TICAM2 is named in the same sentence as 19 diseases in open-access papers, as found by Europe PMC text mining. Sharing a sentence is not in itself a finding about the gene and the disease. The quoted sentences say what the papers report.
SARS-CoV infection (2 papers, 2017 to 2022). "We confirmed that Ticam2, a TLR adapter protein specific to TLR4,contributes to SARS-CoV pathogenesis by showing that Ticam2−/−mice have increased susceptibility to SARS-CoV infection." (PMID 28592648, 2017). "In addition, allelic variation in the TLR adaptor protein, Ticam2, influences susceptibility to SARS-CoV infection in mice as Ticam2−/− mice had high susceptibility to SARS-CoV-2 infection." (PMID 35956081, 2022). "We identified Ticam2, an adaptor protein in the TLRsignaling pathways, as a candidate driving differential disease at the Chr 18 locus.Ticam2−/− mice were highly susceptible to SARS-CoVinfection, exhibiting increased weight loss and more pulmonary hemorrhage than controlmice." (PMID 28592648, 2017).
cystitis (1 paper, 2017). Inflammation of the urinary bladder. "In the down-regulated candidate genes, GJC1 and TICAM2 demonstrated the most statistically significant association with cystitis (rawP = 6.77e-05, adjP = 3.40e-04)." (PMID 28899343, 2017).
lupus (1 paper, 2017). "The importance of interferons was highlighted in our previous results on the TLR4 signaling pathway, where TLR4, TICAM1, TICAM2, TBK1, IRF3, IFNA1, and IFNA2 mRNAs showed changes in the murine lupus-like models." (PMID 29349090, 2017).
otitis (1 paper, 2021). "This analysis revealed that TICAM2 expression was decreased by more than two-fold in the otitis-prone group." (PMID 34360632, 2021). "In a study that divided AOM children into otitis-prone and non-otitis prone groups, middle ear fluid was collected by tympanocentesis, and TICAM2 (Toll-like receptor adapter molecule 2) expression in both groups was compared using reverse transcription polymerase chain reaction (RT-PCR)." (PMID 34360632, 2021).
Pulmonary hemorrhage (1 paper, 2017). Pulmonary hemorrhage is a bleeding within the lungs. "In contrast, pulmonary hemorrhage scoreswere significantly higher in Ticam2−/− mice at 4 dpostinfection." (PMID 28592648, 2017). "Ticam2−/−mice were used to confirm the role of that gene in contributing to SARS-CoV-induced weightloss and pulmonary hemorrhage, although not vascular cuffing." (PMID 28592648, 2017).
Sepsis (1 paper, 2020). Sepsis is defined as life-threatening organ dysfunction caused by a dysregulated host response to infection. "Our study suggests that TICAM2 may serve as a potential target in the future development of therapeutic strategies for the treatment of systemic inflammation and sepsis." (PMID 32873853, 2020). "Together, our data provide an important initial clue that TICAM-2 mediated STAT1 activation via SFK is at least partially involved in the establishment of neutrophil exhaustion and sepsis severity." (PMID 32873853, 2020). "In the present study, we examined the role of TICAM2 (TRAM), which is an adaptor protein necessary for the recruitment of TRIF in the MyD88-independent pathway, in neutrophil exhaustion related to sepsis." (PMID 32873853, 2020). "Together, our results shed light on the significance of the less defined TICAM2 (TRAM)-pathway in neutrophil exhaustion related to systemic inflammation and sepsis pathogenesis." (PMID 32873853, 2020). "WT and TICAM2 KO mice were fed with 4% DSS water for 6 consecutive days to chemically induce acute and severe gut damage, leading to systemic inflammation and multi-organ injury reminiscent of sepsis." (PMID 32873853, 2020).
tumor (7 papers, 2015 to 2024). "On the contrary, protein expressions of CAMK2A and TICAM2 were located primarily in normal tissues and weakly expressed in tumor tissues." (PMID 36253777, 2022). "Two additional genes (CD14 and CSNK2A1) were dysregulated in MSS tumours and two genes (CARD11 and VCAM1) were downregulated and six genes were upregulated (LYN, TICAM2, ICAM1, IL1B, CCL4 and PTGS2) in MSI tumours." (PMID 29188362, 2018).
infection (6 papers, 2014 to 2025). The state of being infected such as from the introduction of a foreign agent such as serum, vaccine, antigenic substance or organism. "But, in presence of amlexanox which prevented cellular TBK expression, STING and TICAM2 were phosphorylated in infection, but IRF3 phosphorylation was inhibited." (PMID 30770800, 2019). "Infection with NH/P68 also caused down-regulation of IFNAR1 and NLRP3 receptors, MYD88 adaptor proteins, as well as other molecules involved in modulating receptor signaling pathways (JUN, PELI1, TBK1, and TICAM2)." (PMID 40530033, 2025). "Here we showed an adaptor molecule TICAM2 binds with STING for optimum infection." (PMID 30770800, 2019). "Neither phospho-STING, nor phospho-TICAM2 were detected in uninfected cells, but at 12 h post-infection, immunoprecipitated sample expressed phsopho-STING, and phospho-TICAM2." (PMID 30770800, 2019). "Transient transfection of AKT1DD(308D473D), or AKT2DD initiated phosphorylation of cellular STING and TICAM2 even in absence of infection, which was inhibited by dominant-negative AKT1AAA(K179A/T308A/S473A) or AKT2AAA." (PMID 30770800, 2019). "However, in RAW 264.7 cells transduced with positive control shRNAs to knock down gene expression of IFN-γ receptor 1 (Ifngr1), 2 (Ifngr2) or Ticam2, the antiviral control by IFN-γ was greatly compromised and a 3- to 4-fold increase of infection efficiency was observed." (PMID 25268627, 2014). "Phosphorylation of STING, and TICAM2 were inhibited, but not IRF3 phosphorylation by AKT inhibitor IV after infection." (PMID 30770800, 2019).
cancer (4 papers, 2012 to 2025). A tumor composed of atypical neoplastic, often pleomorphic cells that invade other tissues. "According to the KEGG analysis, CHST11 may participate in PD‐L1 expression and PD‐1 checkpoint pathway in cancer by regulating genes TICAM2, LAT, TLR2, CD4, STAT3, NFKBIE and CD3D." (PMID 36062845, 2023). "However, in this cluster, the AZIN1 and TICAM2 were down-regulated and were lacking direct experimental evidence to support their regulation with HIF or hypoxia during cancer." (PMID 23122428, 2012).
adenocarcinoma (1 paper, 2012). A common cancer characterized by the presence of malignant glandular cells. "The TICAM2 physically bridged toll like receptor-4 (TLR4) with TICAM1 and the TLR4 partially regulated by the HIF during adenocarcinoma." (PMID 23122428, 2012).
TICAM2 also shares sentences with these, for which no sentence is quoted: fungal infections (1 paper); gastric cancer (1); iron deficiency (1); ischemia (1); latent infection (1); melanoma (1); skin melanoma (1); spinal cord ischemia (1); tuberculosis (1).